CEMP1 (cementum protein 1)
Description:
May play a role in development of the periodontium which surrounds and supports the teeth by promoting the differentiation of multi-potent cells from the periodontal ligament into cementoblasts to form the cementum. Binds hydroxyapatite and may promote the biomineralization of the cementum. Also promotes cell proliferation.
Synonyms: CP-23; CP23
Tractability: No criterion of Open Targets' tractability assessment is met for any kind of drug.
Gene: Protein-coding gene on chromosome 16 (2,530,035 to 2,531,417, reverse strand). Ensembl gene ENSG00000205923.
Subcellular location: Cytoplasm; Nucleus
Subcellular location (Human Protein Atlas): Nucleoplasm
Gene Ontology:
Molecular function: hydroxyapatite binding; protein binding
Biological process: biomineral tissue development; cell differentiation; cell population proliferation; odontogenesis
Cellular component: cytoplasm; nucleus
Genetic constraint (gnomAD): Missense variants: 387 observed, 331.87 expected, observed/expected ratio (o/e) 1.17, 90% interval 1.07 to 1.27. Synonymous variants: 161 observed, 135.48 expected, observed/expected ratio (o/e) 1.19, 90% interval 1.04 to 1.35.
Diseases named in the same sentence as CEMP1 in open-access papers:
CEMP1 is named in the same sentence as 14 diseases in open-access papers, as found by Europe PMC text mining. Sharing a sentence is not in itself a finding about the gene and the disease. The quoted sentences say what the papers report.
periodontal disease (2 papers, 2013 to 2019). "Therefore, CEMP1 might be a key component that coordinates precisely in temporal and spatial relationships in order to reconstruct the architecture and function of bone and the periodontal tissues previously affected by periodontal disease." (PMID 24265720, 2013).
breast carcinoma (1 paper, 2015). "The breast cancer cell line MCF7 showed the highest CEMP1 expression (0.6 fold), followed by two rhabdomyosarcoma cell lines (RH28 (0.18 fold) and RD (0.18 fold))." (PMID 26011628, 2015).
leukemia (1 paper, 2015). A malignant (clonal) hematologic disorder, involving hematopoietic stem cells and characterized by the presence of primitive or atypical myeloid or lymphoid cells in the bone marrow and the blood. "We also determined that the region spanning the CEMP1 locus is commonly amplified in a variety of cancers, and finally we found significant overexpression of CEMP1 in leukemia, cervix, breast, prostate and lung cancer." (PMID 26011628, 2015). "CEMP1 expression was found in additional oral, breast, cervical, prostate and lung cancer samples, as well as leukemia samples." (PMID 26011628, 2015). "Furthermore, we found that CEMP1 is over expressed in several cancer cell lines and it was determined that the chromosomal region spanning the CEMP1 locus is commonly amplified in a variety of cancers, like leukemia, cervix, breast, prostate and lung cancer." (PMID 26011628, 2015).
prostate carcinoma (1 paper, 2015). A carcinoma that arises from epithelial cells of the prostate gland. "Previous studies have shown expression of CEMP1 in breast and prostate cancer with bone metastasis and in MCF-7 and PC3 cell lines." (PMID 26011628, 2015).
tumor (2 papers, 2015 to 2018). "Since CEMP1 is expressed in several cancer cell lines, we wanted to expand these studies to human tumor samples and their normal tissue counterparts contained in publicly available microarray databases." (PMID 26011628, 2015). "This possibility is further supported by the fact that the original CEMP1 protein was isolated and characterized from a human cementoblastoma, a neoplasm of odontogenic ectomesenchyme origin.." (PMID 26011628, 2015). "Our results show that CEMP1 expression in fibroblast growing in non-mineralizing media changed normal mouse and human cells into transformed cells, showing cancerous phenotypes in all tested in vitro tumor-forming assays." (PMID 26011628, 2015).
cancer (1 paper, 2015). A tumor composed of atypical neoplastic, often pleomorphic cells that invade other tissues. "Our findings suggest that CEMP1 exerts modulation of a number of cellular genes, cellular development, cellular growth, cell death, and cell cycle, and molecules associated with cancer." (PMID 26011628, 2015). "Our results suggest that CEMP1 functions in the modulation of a number of cellular genes like those involved in development, growth, cell death, cell cycle and molecules associated with cancer." (PMID 26011628, 2015). "Based on the results obtained in this study, the cellular functions altered by the presence of CEMP1 appear to be associated with some aspects of cancer development, thus sustaining the idea that CEMP1, similar to some growth factors, could also function as an oncogene." (PMID 26011628, 2015). "More research needs to be carried on to fully understand the role of CEMP1, if any, on cancer development." (PMID 26011628, 2015). "Several mRNAs whose expression is modified by CEMP1 overexpression in these cells were identified and several of these genes are involved in cancer." (PMID 26011628, 2015). "Given the results presented above suggesting an oncogenic role for CEMP1, we decided to evaluate CEMP1 expression on a variety of human cancer cell lines by qRT-PCR and Western Blot." (PMID 26011628, 2015). "The results show CEMP1 expression in all cancer cell lines tested, both at the mRNA and protein levels." (PMID 26011628, 2015). "However all cancer cell lines tested, showed increase expression of CEMP1 at some level, and some of them expressed CEMP1 at higher levels than the cementoblastic-like cell line." (PMID 26011628, 2015). "There is not much information related to the role of CEMP1 in cancer." (PMID 26011628, 2015).
CEMP1 also shares sentences with these, for which no sentence is quoted: cryptosporidiosis (7 papers); infection (3); AIDS (1); asphyxia (1); epilepsy (1); Giardia infection (1); lung carcinoma (1); rhabdomyosarcoma (1).